TGFBR1 (transforming growth factor beta receptor 1)
Diseases named in the same sentence as TGFBR1 in open-access papers (continued):
Sharing a sentence is not in itself a finding about the gene and the disease.
cancer (continued). "As such, special attention in future analyses should be paid to the linking genes PRKCA, PTPN14, POU2F1, and TGFBR1, because of their possible roles in cancer initiation." (PMID 30045691, 2018). "Nevertheless, we found that either TGF‐β1 neutralization or Tgfbr1 depletion in cancer cells significantly abolished Il‐17rb up‐regulation, suggesting a critical role of TGF‐β1 in up‐regulating Il‐17rb expression in cancer cells in the TDLNs." (PMID 28993429, 2017). "To further demonstrate that TGF‐β1 plays a critical role in promoting tumorigenic ability of cancer cells in the TDLNs, we performed co‐culture experiments using Tgfbr1‐depleted or non‐depleted 4T1 cells with cells from the TDLNs." (PMID 28993429, 2017). "The small molecule TGFBR1 inhibitor Galunisertib is being evaluated in cancer patients with unmet need." (PMID 27835901, 2016). "The isolated primary cancer cells from the Tgfbr1/Pten 2cKO mice retain higher expression of IL-13Rα2 as compared to other tissues, including the spleen, lung, kidney, liver, and skin." (PMID 23421960, 2013). "In the present study, we explored the association between the TGFBR1*6A and IVS7+24G>A polymorphisms and cancer risk, involving 35 eligible case–control studies." (PMID 22905183, 2012). "The TGF-beta receptor type I (encoded by the TGFBR1 gene) is a mediator of TGF-beta growth-inhibitory signals and has been targeted in several studies of cancer susceptibility and progression, with frequently discordant results." (PMID 22292045, 2012). "Odds ratio (OR) and 95% confidence interval (CI) were applied to assess the associations between TGFBR1*6A and IVS7+24G>A polymorphisms and cancer risk." (PMID 22905183, 2012). "Proteins known to be involved in growth signals, thus leading to self-sufficiency in cancer cells, such as TGFBR1, EGFR, IGFR1R, GRB2, are in the ‘hubs’ of CGN." (PMID 23166660, 2012). "In cancer cells, TGFBR1 exhibits a dual role depending on the tumor stage." (PMID 40725247, 2025). "However, in advanced stages, the overexpression or constitutive activation of TGFBR1 can facilitate cancer progression by promoting epithelial mesenchymal transition (EMT), invasion, metastasis, and immune evasion." (PMID 40725247, 2025). "Strikingly, ACACA expression exhibited significant negative correlations with the immune checkpoint-related genes (PDCD1, LAG3, LAGLS9, IDO1, CD244, CTLA4 and TIGIT), while showing positive associations with other genes (TGFBR1, KDR, IL10RB, CD160 and CD274) across most cancer types." (PMID 41169354, 2025). "However, our study highlights an alternative, cholesterol-independent mechanism by which NPC1 interacts with TGFBR1 to promote cancer progression." (PMID 39762312, 2025). "Furthermore, the expression of CD276, MICB, PVR, TGFB1, and TGFBR1 displayed high correlations with TUBA1B expression in most cancers." (PMID 38589634, 2024). "ENST00000311534 was significantly correlated with HMGB1, ENST00000326094 was significantly correlated with BTN3A1, CD160, TGFBR1, and IL6R, and ENST00000375991 was significantly correlated with CD276, ENTPD1, HMGB1, TLR4, KDR, and TGFBR1 among these 33 immune genes in more than 20 cancer types." (PMID 39766805, 2024). "Furthermore, RBFOX2 expression showed a significant association with immunosuppressive genes like PD-L1, CTLA4, VTCN1, KDR, and TGFBR1 across different types of cancers." (PMID 38881877, 2024). "ISCA1 was correlated with ENTPD1, HMGB1, TLR4, and TGFBR1 in more cancers." (PMID 39766805, 2024). "Numerous cancer cell lines had imbalanced expression levels of TGFBR1 and TGFBR2." (PMID 38753874, 2024).
cancer (continued). "In addition, DHX9 expression in most cancer types had an obvious positive correlation with several checkpoints, such as TGFBR1 (transforming growth factor-beta receptor 1), KDR (vascular endothelial growth factor receptor-2, VEGFR-2), and CD274 (PD-L1)." (PMID 37214432, 2023). "In addition, the results uncovered that the expression of ADAM17 was positively correlated with an immunostimulator (IL6R) and immunoinhibitors (CD274, KDR, TGFBR1) in most cancer types." (PMID 35720350, 2022). "The activation or overexpression of TGFBR1 is found in various types of cancer." (PMID 33413277, 2021). "FoxO could inhibit T cell effector function through inhibition of T-bet expression; CD244 could be indicative of an exhausted phenotype and is related to cancer immune tolerance; and finally TGFBR1 is the main receptor for the immunosuppressive cytokine TGFβ." (PMID 33076479, 2020). "TGFBR1 is a widely investigated oncogene in human cancers, including HCC." (PMID 32404179, 2020). "In this study, we showed that TGFBR1 has a strong inverse correlation with RKIP/PEBP1, suggesting that the elevated expression of RKIP/PEBP1 may decrease TGFBR1 and suppress cancer progression induced by TGFBR1-dependent signaling." (PMID 30115852, 2018). "The EGFR and the TGFBR1 signalling pathways alone play a role in cancer development." (PMID 28719611, 2017). "Moreover, Transfection of A549 and H157 cells with pEGFP-C1 plasmid containing TGFBR1 CDS sequence significantly promoted the cell viability cancer cell migration and invasion (p < 0.05)." (PMID 29371929, 2017). "Accordingly, the two interacting SNPs could affect expression of the two cancer-associated proteins, TGFBR1 and SMAD7, participating in the same TGF-β signaling pathway, but affecting multiple cancer hallmarks." (PMID 27588484, 2016). "With such resemblance to human HNSCCs, the Tgfbr1/Pten 2cKO mice could be useful for screening novel therapeutics against cancer." (PMID 23421960, 2013). "Characteristics of case-control studies included in TGFBR1 IVS7+24G>A polymorphism and cancer risk." (PMID 22905183, 2012). "Thus TGFBR1*6A genotypes mya be specifically related to only certain kinds of cancer, in a population- and tissue-related manner." (PMID 20429896, 2010). "Additionally, TGFB1/TGFBR1 exhibited positive correlations with CILP2 in nearly all cancer types." (PMID 38136386, 2023). "In addition, String pathway interaction analysis identified six proteins (TGFBR2, TGFA, FGF21, SMAD4, TGFBR1, and FZD3) that were at the intersection of the cancer-associated pathways and, importantly, which were restored to their younger crosstalks by the rounds of TPE." (PMID 35999337, 2022). "Interestingly, high expression of TGFBR1 in several forms of cancers, including colorectal carcinoma, glioma, lung squamous carcinoma, pancreatic adenocarcinoma, stomach adenocarcinoma and invasive breast carcinoma, has been shown to correlate with poor survival." (PMID 35853811, 2022). "Notably, FUT11, BGLAP, SSR2, TGFBR1, BSG, and FUCA1 have been reported to be associated with related cancer, but no studies showed the functions of other eight DESPGs in corresponding cancers." (PMID 31824949, 2019). "Immune-modulating proteins such as CXCR4, CD40, IL7R, TGFBR1, and SEMA4D are frequently targeted for cancer intervention studies." (PMID 40805206, 2025). "The distinct roles of TGFBR1 and TGFBR2 in cancer, especially as they pertain to immune regulation in GBM, remain undetermined." (PMID 40277917, 2025). "According to multiple pan-cancer analyses, SHCBP1 expression is also positively associated with TMB, MSI, immune cell infiltration values, and the expression of immunosuppression-related genes, such as TGFBR1, PD-L1, and TGFB1 in various cancers." (PMID 41009347, 2025). "Reintroducing NPC1 (P691S) restored TGFBR1 levels and cell migration, highlighting a cholesterol-independent function for NPC1 in cancer progression." (PMID 39762312, 2025).
cancer (continued). "This robust correlation supports the likelihood of imbalanced protein expression of TGFBR1 and TGFBR2 in cancer cell lines." (PMID 38753874, 2024). "In the present study, our analysis has shown that CD276 expression was positively correlated with a number of immune checkpoint genes, including TGFBR1, TGFB1, NECTIN2, IL10RB and CSF1R, in most types of cancer." (PMID 36717836, 2023). "The Wound-Healing proteins TGFBR1 and SMAD link apoptosis, cell transformation into cancer stem cells, and invasiveness through their different functions." (PMID 36672169, 2023). "(E) Integrative analysis of RNAscope and mfIHC data indicates that cancer tissues with high levels of VPS9D1-AS1 had higher levels of TGF-β, TGFBR1, and SMAD1/5/9 than these with low levels of VPS9D1-AS1." (PMID 36458816, 2022). "Together, the present study confirms that TGFBR1 is a novel target of BBR, which extends our understanding of the pharmacological actions of BBR in suppressing lung metastasis of cancer cells." (PMID 35784732, 2022). "Analysis of the site of expression revealed the existence of AKT1, MTDH, and NCOR2 genes in the colorectum and presence of TGFBR1 and MTDH in various cancer cell lines such as A-549 and HeLa." (PMID 36499586, 2022). "Other immune checkpoint-related genes as CD28, TGFBR1, and TNFSF4 (OX40L) have been frequently reported to engage in cancer immune regulation in ICI research." (PMID 34897033, 2021). "It is encouraging that the addition of TGFBR1 inhibitors can restore the cytotoxic phenotype of NK cells, which highlights the potential of TGFBR1 and the TGF-β pathway in cancer treatment." (PMID 33114183, 2020). "Conversely, 28 of cancer-related genes were downregulated by shNrf1, of which 6 genes (i.e., HIF1A, STAT5B, IGF1R, TGFBR1, ATRN, and FZD6) were upregulated by Nrf1α−/− to varying extents." (PMID 32273945, 2020). "TGFBR1 is an important element of the TGF-β/SMAD signaling pathway, which has emerged as a central mediator of cancer progression due to its capacity to regulate cell growth, differentiation and migration." (PMID 29371929, 2017). "We previously reported that the loss of Tgfbr1 and Pten results in cellular senescence evasion, cancer-related inflammation, and expansion of the CSCs in the basilar epithelial layer in SCCHN of the Tgfbr1/Pten 2cKO mice." (PMID 28865486, 2017). "We found that miR-133a can suppress cancer cell invasion, metastasis and proliferation abilities, and we also found that inhibition of IGF-1R and TGFBR1 reduces both cell invasion and cell proliferation." (PMID 24816813, 2014). "However, we concluded that factors other than alternative splicing might account for the association of this polymorphism with cancer, although we cannot rule out the possibility that Int7G24A variant is a marker representing a TGFBR1 haplotype." (PMID 19930569, 2009). "Among other genes that encode immune inhibitors, IL10, TGFBR1, and IDO1 exhibited a broadly negative correlation across most cancer types, aligning with the expression pattern of PEBP1/STK11." (PMID 40806276, 2025). "The downregulation of TGFBR1 and p-SMAD2/3 suggests the suppression of TGF-β signaling, which may contribute to the reversal of CAF activation and the inhibition of cancer-promoting effects." (PMID 38910148, 2024). "Importantly, previous work has demonstrated a high correlation between protein and RNA data for TGFBR1 and TGFBR2 within the same cell line (Spearman’s correlation: 0.672 for TGFBR1, 0.771 for TGFBR2), based on comprehensive data from 375 cancer cell lines." (PMID 38753874, 2024). "Such a scenario suggests that in cancer and EMT, TGF-β signaling could undergo modulation in trans by TGFBR1/ACVR1 signaling." (PMID 38753874, 2024). "When TGFBR1 was inhibited, the inhibitory effect of BBR on trans-endothelial migration of AsPC-1 cells was blunted, indicating that BBR prevented the trans-endothelial migration of cancer cells by interrupting TGF-β1 signaling." (PMID 35784732, 2022).
cancer (continued). "Specifically, researchers found that these miRNAs inactivated the TGF- β signaling pathway (an oncogenic pathway in later cancer stages) via targeting several important factors, including SMAD2, SMAD4, and TGFBR1 (for miR-582-3p); and SMAD2, TGFBR1, as well as TGFBR2 (for miR-582-5p)." (PMID 35011442, 2021). "In melanoma, the treatment mediated by TGFBR1 inhibitor SB505124 in the presence of IL-12 overexpression demonstrates enhanced immune responses, and NK1.1 is a potential biomarker for increased effector cells and enhanced cancer-killing effects." (PMID 33114183, 2020). "As the expression of TGFβ receptors (TGFBR1, 2 and 3) was upregulated in CAF-S1 cells compared to CAF-S4, we compared the impact of TGFBR inhibitor on CAF-S1- and CAF-S4-induced EMT initiation on cancer cells." (PMID 31964880, 2020). "SMAD2/3 is a downstream mediator of TGFBR1 and the activation of AKT is considered the main downstream signal of IGF-1R, both SMAD2/3 and p-AKT participate in the process of cancer progression by promoting cell growth, anti-apoptotic effects, and cell invasion." (PMID 31035970, 2019). "We demonstrated previously that autocrine signalling through TGFBR1, is required for transformation of rodent fibroblasts by oncogenic BRAF, but did not investigate this dependence in human models of activated RAS/RAF-driven cancer." (PMID 27835901, 2016). "Among familial non-HNPCC cases the average age at cancer diagnosis in TGFBR1*6A carriers and non-carriers was 58.4 years (s.d., 13.0) and 56.8 years (s.d., 10.6), respectively." (PMID 19401691, 2009). "Furthermore, recent research in cancer cell lines suggested that some miRNAs, such as miR-133b and miR-20b-5p, can inhibit the epithelial-mesenchymal transition (EMT) induced by TGF-β1 by targeting, respectively, TGFBR1 and TGFBR2 genes." (PMID 33905626, 2021). "This inhibitor is deemed tolerable, with an acceptable margin of safety when administered using intermittent dosing regimens, demonstrating that TGFBR1 inhibitors are suitable for clinical use and may provide new opportunities for therapy of BRAF-inhibitor resistant cancer." (PMID 27835901, 2016). "Similarly, in agreement with nintedanib's inhibitory effect on TGFBR1 activity as well as SMAD phosphorylation and EMT in our analyses, multiple studies report a lack of EMT induction after nintedanib treatment in cancer cell lines in vitro and in mouse models of cancer in vivo." (PMID 27036020, 2016). "These genes have various implications for cancer therapy, and the detailed mechanism of action of DLG3, TGFB3, TGFBR1 and FZD6 genes in GC has not been studied, and needs further researches to explore." (PMID 36712672, 2022).
infection (16 papers, 2006 to 2025). The state of being infected such as from the introduction of a foreign agent such as serum, vaccine, antigenic substance or organism. "At the acute stage of infection, we found that TGFΒ1 and the related genes TGFBR1, SMAD 3/4 were all up-regulated, and maintained thereafter (because we didn’t detect them as DEGS in T3vsT2)." (PMID 27661612, 2016). "Using an NHP model of barcoded SIVmac239 intravenous infection and therapeutic dosing of anti-TGFBR1 inhibitor galunisertib (LY2157299), we confirm the latency reversal properties of in vivo TGF-β blockade, decrease viral reservoirs and stimulate immune responses." (PMID 38355731, 2024). "In support of studies reporting increased susceptibility to infection with AUD, we report down-regulation of a number of genes important for host defense such as cytokines (IL1R1 and TNFSF11), chemokines (CCL2), and receptors (TGFBR1 and TLR8)." (PMID 27427759, 2016). "The number of activated T cells (subset 2) increased substantially after infection with upregulation of the IFNG, STAT3, STAT4, IL9, FOXP3, and TGFBR1, TGFBR2 genes." (PMID 40573402, 2025). "Expression of Tgfbr1, Hexb, Golm1, and Sall1 increase with microglia maturity, and maturation is dependent on TGF-β signaling which was up-regulated by maternal infection." (PMID 38730262, 2024). "Moreover, ubiquitination of endogenous TGFBR1 and TGFBR2 was markedly elevated by the overexpression of SMURF2WT, but it was decreased by the enforced infection of SMURF2T249A in TGS-01 GSCs." (PMID 35017630, 2022).
connective tissue disorder (12 papers, 2013 to 2026). A disease involving the connective tissue. "Loeys‐Dietz syndrome (LDS) is a systemic connective tissue disorder caused by pathogenic variants in TGFBR1 or TGFBR2, characterized by arterial tortuosity, aneurysms, and skeletal and craniofacial abnormalities." (PMID 41426201, 2026). "Loeys‐Dietz syndrome (LDS) is an autosomal dominant connective tissue disorder caused by pathogenic variants in TGFBR1 or TGFBR2." (PMID 41426201, 2026). "LDS is a rare, multi-system connective tissue disorder caused by an autosomal dominant, heterozygous mutation of TGFBR1 or TGFBR2." (PMID 33289867, 2020). "For this reason, the same revised Ghent nosology recommends supplementing genetic tests with analyses of TGFBR1, TGFBR2, COL3A1, and collagen biochemistry, especially when symptoms of MFS overlap with those of other connective tissue disorders." (PMID 37688493, 2024).
kidney disease (7 papers, 2007 to 2025). "Notably, mitigating the mitochondrial injury in GECs also attenuated TGFBR1-induced podocyte loss in transgenic mice, underscoring the intricate involvement of crosstalk between signaling pathways and between glomerular cells and in kidney disease development." (PMID 39990662, 2025). "Experimental approaches to TGF-β receptor inhibition in kidney disease include small-molecule kinase inhibitors of ALK5 (TGFBR1) and function-blocking monoclonal antibodies against TGFBR2." (PMID 39990662, 2025). "Therefore, miR-140-5p may have a therapeutic potential for preventing fibrotic kidney diseases through inhibiting the TGF-β1/Smad signaling pathway by directly targeting TGFBR1." (PMID 33013464, 2020).
cardiovascular disease (6 papers, 2014 to 2025). "There are 20 unique genes within the 9q22.33 locus and three genes (TGFBR1, NR4A3, and INVS) were linked to cardiovascular diseases." (PMID 28710368, 2017). "Although TGFBR1 has been extensively studied in cardiovascular diseases, its role and mechanism in HFpEF remain unclear." (PMID 40880411, 2025). "TGFBR1 has been reported to regulate cardiovascular disease." (PMID 32528555, 2020). "Heterozygous mice did not display a cardiovascular disease phenotype, which is in line with previous findings in both Tgfbr1 and Tgfbr2 knock-out mouse models." (PMID 24587008, 2014).
adenocarcinoma (5 papers, 2010 to 2023). A common cancer characterized by the presence of malignant glandular cells. "Consistent with previous studies, the major consequence of Tgfbr1 loss on tumourigenesis was the development of invasive adenocarcinomas with E-cadherin+ve cells at the invasive front." (PMID 28622298, 2017). "We assessed the frequency of constitutively decreased TGFBR1 allelic expression and association with SNPs covering the TGFBR1 locus using RNA and DNA extracted from the peripheral blood lymphocytes of 118 consecutive patients with biopsy-proven adenocarcinoma of the colon or the rectum." (PMID 20500843, 2010).
vasculopathies (3 papers, 2014 to 2024). "Similar to other conditions known as TGF-β vasculopathies (MFS, which is caused by FBN1 mutations and LDS, which is caused by TGFBR1, TGFBR2, SMAD3 and TGFB2 mutations), the SLC2A10 loss of function activates the TGF-β signaling pathway." (PMID 25373504, 2014).
neurological diseases (2 papers, 2010 to 2023). "Among the top 50 database-predicted targeted genes, 8 genes (HOMER1, FRAT2, GRM5, TGFBR1, KDM3A, RGS2, ARRB1, and YWHAZ) were reported to be associated with axonal/neuronal regeneration/or neurological diseases." (PMID 36959678, 2023). "The binding of HSA to astrocyte TGFBR1 and TGFBR2 following BBB disruption is associated with seizures in several neurological diseases." (PMID 20529383, 2010).